SRF (serum response factor)
Diseases named in the same sentence as SRF in open-access papers (continued):
Sharing a sentence is not in itself a finding about the gene and the disease.
tumor (continued). "The most plausible mechanism for RAC1/P29S in tumor progression is through activation of the serum response factor/myocardin-related transcription factor (SRF/MTRF) transcriptional programs, which lead to mesenchymal transition of melanocytes." (PMID 35454871, 2022). "IGF2BP1 promotes SRF expression in an m6A dependent manner, enhances SRF dependent transcriptional activity at the post-transcriptional level, and promotes tumor cell proliferation and invasion." (PMID 35022030, 2022). "Exploration of the follow-up data regarding SRF-fused tumors demonstrates that neoplasms harboring SRF rearrangements have a generally benign behavior, regardless of SRF partner genes." (PMID 36421692, 2022). "Accumulating evidence suggests that SRF is involved in the carcinogenesis and tumor progression of various neoplasms, especially in the mesenchymal transition of epithelial cells." (PMID 36421692, 2022). "We performed IHC staining on 55 CRC tissue samples for SRF, and the results showed that SRF was highly expressed not only in CRC tissues but also around tumor blood vessels." (PMID 35198444, 2022). "This specific SRF signature is shared by tumor subtypes carrying other SRF-fused partner genes, such as the perivascular tumors harboring SRF::RELA fusion." (PMID 36421692, 2022). "IGF2BP1 promotes the expression of serum response factor (SRF) and its target genes in a m6A-dependent manner, enhances the expression of tumor genes and promotes the proliferation, migration and invasion of HCC cells." (PMID 35936671, 2022). "Myocardin-related transcription factors (MRTF), which are co-activators of serum response factor (SRF), are linked to epithelial-mesenchymal transition (EMT) and tumor metastasis." (PMID 35371070, 2022). "Supervised analysis on MN tumor samples identified 2,249 differentially expressed genes (p-value < 0.05) in SRF-fused positive tumors with respect to EWSR1-fused positive tumors." (PMID 36421692, 2022). "Surprisingly, there was a main effect for both stretch (p = 0.035) and C26 tumor-derived factors (p < 0.001) to decrease SRF protein expression." (PMID 34395422, 2021). "Our novel observation that LINC complex disruption leads to increased MKL1 nuclear translocation suggests crosstalk between LINC complex and SRF-MKL pathway and an important role of SRF-MKL driven gene transcription in 1D tumor cell motility." (PMID 34205257, 2021). "MRTF-A is a co-activator of serum response factor (SRF) that functions as a tumor-promoting factor in increasing proliferation, and metastasis as well as triggering drug resistance." (PMID 33652780, 2021). "IGF2BP1 deletion disrupts with SRF/TCF- and SRF/MRTF-dependent transcriptional regulation in tumour cells through decreasing the richness of intracellular SRF." (PMID 34794452, 2021). "Future studies are required to identify specific SRF-MKL transcriptional genes involved in tumor cell motility in physiological environments." (PMID 34205257, 2021). "Using RNA sequencing of tumor samples, Antonescu and colleagues reported somatic serum-response factor (SRF) fusion genes in IM, including SRF-RELA." (PMID 32888134, 2021). "MKL1 is a well-known coactivator of SRF (serum response factor), which mediates the transcription of multiple genes involved in diverse cellular processes, such as cell migration and tumor metastasis 38-40." (PMID 33061800, 2020). "SRF-dependent transcriptional regulation is a key modulator of cytoskeletal dynamics and was shown to promote tumor cell invasion and experimental metastasis, as recently shown for IGF2BP1 in EOC-derived cells." (PMID 30371874, 2019). "The tumor targeting of FA-SRF-BSANPs was significantly higher than those of SRF-BSANPs and SRF-solution in nude mice." (PMID 30744448, 2019).
tumor (continued). "A comparison of the distribution of MCM genes between tumor and adjacent normal lung tissues showed MCM2-8 and MCM10 to be significantly up-regulated in LUAD tumor tissues in TCGA cohorts, whereas the SRF and MCM9 were significantly down-regulated in the same." (PMID 31323040, 2019). "How IGF2BP1 or SRF influence tumor cell viability at low adhesion and mitogen stimulation (FBS, 1%) was analyzed by anoikis resistance assays upon depleting both factors in ES-2 cells." (PMID 30371874, 2019). "In summary, these findings demonstrate that IGF2BP1 promotes SRF-dependent transcriptional regulation and that both factors likely synergize in promoting an ‘aggressive’ tumor cell phenotype." (PMID 30371874, 2019). "In conclusion, these findings indicate that the SRF/IGF2BP1-dependent control of gene expression in cancer is largely conserved, promotes the synthesis of factors enhancing tumor cell growth and is associated with unfavorable prognosis in three solid cancers." (PMID 30371874, 2019). "The end targets of these pathways, including cytokines (IL1A/B, IL6, IL8, IL18) and genes related to cell proliferation (JUN, SRF), were upregulated, suggesting that the activation of these TLRs leads to tumor growth." (PMID 29912993, 2018). "These mutated genes include serum response factor (SRF) and PPP2R5D, which were detected in individual tumor samples." (PMID 30093687, 2018). "Taken together this indicates that indirect effects via Mal/SRF signalling are rate-limiting for invasion of RasV12/pico tumours." (PMID 28346426, 2017). "MRTF-A, co-activators of serum response factor (SRF), promoted tumor cell invasion and metastasis in cancer." (PMID 28035058, 2017). "It has been recently reported that MRTFs (myocardin-related transcription factors) and SRF (serum response factor) are the downstream factors of Rho GTPases and required for cytoskeletal dynamics and tumor metastasis." (PMID 27121062, 2016). "Syngeneic graft assays again showed that YAP overexpression increased tumour-initiating cell frequency, and SRF or IL6 depletion decreased it." (PMID 26671411, 2015). "Using a limiting dilution xenograft assay, we also found that IL6 overexpression partially rescued the decrease in tumour-initiating activity of MCF-10A H-RasG12V cells induced by YAP/TAZ or SRF knockdown." (PMID 26671411, 2015). "SRF not only exhibited its direct anti-proliferative activity in cell based assays (KB-3-1 and KB-V1), but also demonstrated an anti-tumor activity in vivo in human HCT15-implanted xenografts with an effective dose of SRF (20 mg/kg/day in mice)." (PMID 25354194, 2014). "Compared with tumor growth in control mice, we found that SRF induced a significant reduction of tumor mass by 40% on day 9 in a time-dependent manner, suggesting that SRF potentially suppresses tumor growth in vivo." (PMID 25354194, 2014). "Since TGF-beta expression is transcriptionally regulated by the MRTF-A/SRF axis, it is tempting to speculate that CsA exerts its tumor-promoting effects by this pathway." (PMID 41317652, 2026). "Similarly, SRF was incorporated into mesoporous silica NPs (MMSNs) to generate MMSNs@SO NPs, which inhibited HepG2 tumor cells by depleting GSH, inhibiting intracellular GSH synthesis, and causing cancer cell ferroptosis." (PMID 39276361, 2024). "In vivo, the tumor inhibition rate of SRF@FeShik-GOx-cRGD SNs was 81.5%." (PMID 39276361, 2024). "In addition, the expression of E-cadherin and N-cadherin was significantly decreased and increased, respectively, in tumor-bearing mice overexpressing SRF compared with levels in controls." (PMID 36831659, 2023). "In addition, the phosphorylation of the RPS6KA3 substrates (BAD S118, MTOR S1261, SRF S224, etc.), which involved in the regulation of cell differentiation and the inhibition of apoptotic were upregulated in tumor samples." (PMID 37704624, 2023).
tumor (continued). "However, the researches on regulation of SRF by m6A methylation in tumor are very limited, more researches are needed to clarify the role of m6A methylation in regulating SRF in tumor metabolism." (PMID 35022030, 2022). "Accumulating evidence suggests that SRF may play a role in carcinogenesis and tumor progression in various neoplasms, where it is often involved in different fusion events." (PMID 36421692, 2022). "The knockdown of STAT3 or SRF significantly suppresses tumor invasive properties." (PMID 35538578, 2022). "In tumor cells, SRF can promote cell reprogramming into multifunctional cells." (PMID 35022030, 2022). "IGF2BP1 and SRF exert synergistic effects in promoting tumour invasiveness." (PMID 34794452, 2021). "This suggests a dual role of SRF in the pathogenesis of tumor formation." (PMID 32885587, 2021). "In the regulatory network, several hub genes with maximum intramodular connectivity were identified (i.e., GATA6, SOX17, MEF2C, and SRF), which might propose novel insights for tumor angiogenesis." (PMID 34869004, 2021). "IGF2BP1 could recognize m6A modification and impair the miRNA-dependent downregulation of SRF expression, resulting in tumor cell growth and invasion." (PMID 34226535, 2021). "The conserved target mRNA of IGF2BP1 encodes serum response factor (SRF), a highly conserved and widely expressed transcription factor that participates in cellular properties such as tumour cell growth and migration in a signal- and cytoskeleton-dependent manner." (PMID 34794452, 2021). "As a conservative oncogenic driver network, IGF2BP1 promotes SRF expression in a conservative, m6A-dependent manner by inhibiting miRNA-induced SRF mRNA decay, leading to enhanced transcriptional activity of SRF, promoting tumor cell growth and invasion." (PMID 33552994, 2020). "Therefore, the conservation of IGF2BP1-dependent regulation of SRF expression was analyzed in a panel of four tumor cell lines derived from distinct primary cancers." (PMID 30371874, 2019). "SRF is a transcription factor, which has important roles in tumor progression." (PMID 31370263, 2019). "Despite the obvious, cell type-dependent and variable extent of IGF2BP1/SRF-directed regulation, the presented findings suggested that IGF2BP1 and SRF exhibit similar effects on promoting a pro-proliferative and pro-invasive gene expression signature in tumor cells." (PMID 30371874, 2019). "Thus, in concert with MRTFs and TCFs, SRF serves as a central hub modulating tumor cell migration, invasion and metastasis as well as proliferation and tumor growth in a signaling- and cytoskeleton-dependent manner." (PMID 30371874, 2019). "Taken together, we have identified a previously unknown mechanism by which the nuclear actin pool is regulated and uncovered a previously unknown link of RASSF1A and MRTF‐A/SRF in tumour suppression." (PMID 31414556, 2019). "Cancer cells undergoing partial EMT may acquire enhanced metastatic potential, whereas cancer cells with full EMT (in particular acquiring an SRF-driven mesenchymal phenotype) may instead resemble pericytes to stabilize tumor vasculature." (PMID 28677655, 2017). "Accumulating evidence suggested that SRF may play multiple roles in carcinogenesis and tumor progression in various cancers, specifically in the mesenchymal transition of epithelial tumor cells." (PMID 28947952, 2017). "Further studies of SRF in a variety of xenograft tumor models (for example in KB-3-1- and KB-V1-xenografted mice) might provide insightful information into chemotherapeutic potential of SRF as a novel microtubule-targeting agent." (PMID 25354194, 2014). "In addition to the direct cytotoxicity of SRF to a variety of human cancer cell lines, this antitumoral effect was also examined in animal model using human tumor xenografts in mice." (PMID 25354194, 2014).
tumor (continued). "Within the cytoplasm, LIMK1 may mediate tumor progression via effects on p57Kip2 or serum response factor (SRF), both of which are thought to be directly regulated by cytoplasmic LIMK1, and both of which are known to influence tumor biology." (PMID 21682918, 2011). "Mal/SRF might therefore have a role in promoting tumour growth in humans and it will be interesting to determine whether Mal is ectopically active tumours and whether it is sufficient to drive tissue growth in mouse models." (PMID 20404916, 2010). "Last but not least, SRF, a tumor-associated transcription factor, may also involve in hepatocarcinogenesis induced by COL4A1 and COL4A2." (PMID 31905170, 2020). "Moreover, SRF/IGF2BP1-driven gene expression may also enhance a stem-like tumor cell phenotype, as supported by the recently reported role of SRF in promoting pluripotency and various studies indicating IGF2BPs to sustain stem-like cell properties." (PMID 30371874, 2019). "In addition, blocking SRF expression inhibited tumor proliferation and invasion." (PMID 23426188, 2013). "IGF2BP1 increases SRF expression in an m6A-dependent manner by preventing SRF mRNA degradation by miRNAs and sustaining PDLIM7 and FOXK1 levels, thereby promoting tumour cell proliferation and invasion in OC." (PMID 40356909, 2025). "In summary, tumor cell-derived chemokines and cytokines, such as CXCL1/CXCL8 and SRF, recruit MDSCs, TAMs, Treg and Tex, and interact with target genes, like MIF and IFNG." (PMID 37940972, 2023). "Compared to controls, mice implanted with STAT3- or SRF-downregulated GBM TSs showed reduced normal tissue infiltration and tumor growth, and prolonged survival, indicating a therapeutic response." (PMID 37558923, 2023). "Overexpressed SRF increased OSCC cell migration and invasion in vitro and tumor growth and invasion in vivo." (PMID 36831659, 2023). "Bioluminescence imaging revealed that tumor growth was significantly lower in both STAT3- and SRF-knockdown groups than in the control." (PMID 37558923, 2023). "The number of invading cells, indicated by Zeb1+ cells infiltrating outside the gross tumor mass, was significantly reduced by STAT3 or SRF knockdown." (PMID 37558923, 2023). "ELK4 cooperates with SP1 and SP3 instead of SRF to transcriptionally regulate LRG1, among others, to promote tumor angiogenesis, tumor growth, and metastasis." (PMID 37786278, 2023). "Morphologically, SRF and IGFBP5 were present in the diffuse-type tumor cells, with some overlap with MRTFA+ cells." (PMID 35087207, 2022). "In resistant BCCs, both SRF and MKL1 are required for tumor growth and increase the activity of the Hh pathway." (PMID 35163655, 2022). "SRF, together with MRTF and TCF, can regulate the migration, invasion, growth and proliferation of tumor cells in a signal and cytoskeleton dependent manner." (PMID 35022030, 2022). "SRF and EXOSC3 expression levels were lower in tumor tissues than in control tissues, while RAD51 and EXOC1 were significantly higher in tumor tissues." (PMID 35096059, 2022). "Taken together, these findings support the model in which activated SRF and MKL1 maintain the downstream activity of the Hh pathway and are necessary for resistant tumor growth in BCC." (PMID 35163655, 2022). "In GE2-HCC, top potential transcriptional activators included transcription factors with reported tumour-promoting activity in HCC and/or other cancer types, e.g., NKX6-1, POU2F1/2, cJUN, E2F1, HSF2, SRF, TFCP2 and NFY." (PMID 33541355, 2021). "At the post-transcriptional level, IGF2BP1 maintains the expression of multiple SRF target genes, including PDZ and LIM domain 7 (PDLIM7) and forkhead box K1 (FOXK1), which further enhances tumor cell growth and invasion." (PMID 34692544, 2021). "DMU-214 also downregulated the mRNA and protein levels of serum response factor (SRF) in the SKOV-3 cells, which effectively impaired tumor dissemination." (PMID 34829589, 2021).
tumor (continued). "Inhibition of SRF with the small-molecule inhibitor CCG1423 resulted in enhanced response to enzalutamide in vitro and reduced tumour volume of LuCaP 35CR, a CRPC patient-derived xenograft model." (PMID 33260953, 2020). "With respect to tumor epileptogenicity as well, our GSEA also showed decreased expression of gene sets involved in serum response factor (SRF) signaling in the epileptogenic tumors." (PMID 30621209, 2019). "Induction of SRF by chemerin activated its target gene early growth response-1 (EGR1), a transcription factor, which has been suggested to be a tumor suppressor due to its growth inhibitory and pro-apoptotic effects." (PMID 31370263, 2019). "SRF plays important roles in diverse pathological processes, including EMT-derived tumor metastasis and fibrosis." (PMID 25303231, 2014). "High SRF levels in carcinomas also contribute to ECM degradation and progressive tumor cell migration and invasion." (PMID 23426188, 2013). "Therefore, SRF may enhance the metastatic capability of tumor cells." (PMID 23426188, 2013). "Conversely, SRF activation by over-expressed MRTF family members results in inhibited cell proliferation, and the SRF co activator Myocardin is a tumor suppressor whose expression is reduced in human tumors." (PMID 21573132, 2011). "In a more recent study, quercetin was shown to increase the expression of DUSP5 following binding of the Serum Response Factor (SRF) transcription factor at the DUSP5 promoter to reduce ERK1/2 activity in the nucleus and cell proliferation, resulting in a tumour-suppressive effect." (PMID 40943262, 2025). "In vivo, knockdown of TRIM28 significantly inhibited the tumor growth and overexpression of IDO1 and SRF both could reverse proliferation inhibited by TRIM28 knockdown." (PMID 38947391, 2024). "In addition, staining images showed that the tumor margins were smoother in the STAT3- and SRF-knockdown groups." (PMID 37558923, 2023). "The significantly increased SRF expression in OSCC tissues was positively correlated with tumor progression and lymph node metastasis, suggesting that SRF upregulation in OSCC tissues plays a critical role in tumor invasion and metastasis." (PMID 36831659, 2023). "Furthermore, IGF2BP1 promoted serum response factor (SRF) expression in an m6A-dependent manner, enhancing transcription of SRF-target genes, including PDLIM7 and FOXK1, thereby promoting tumor cell growth and invasion." (PMID 37612540, 2023). "We found, after correcting for tumor volume and location, correlations between the expression level of CD3 or IDH-1 and psychomotor speed; IDH-1, BDNF, ATRX, CK2Beta, GAT-3, NLGN3, SRF, or EAAT1 and memory performance, and P-STAT5b, NLGN3, CK2Beta, or IDH-1 and executive functioning." (PMID 35148403, 2022). "Therefore, the enhanced gene expression of SRF/IGF2BP1 is the driving factor of tumorigenesis and promotes tumour growth and metastasis." (PMID 34794452, 2021). "Finally, downregulated SRF synthesis upon IGF2BP1 deletion was also observed in ES-2-derived Xenograft tumors in nude mice (tumor samples were obtained from)." (PMID 30371874, 2019). "The regulation of SRF-dependent transcription by IGF2BP1 in cancer cells and the partial ‘phenocopy’ observed upon IGF2BP1 and SRF depletion in ES-2 cells suggested that both factors synergize in promoting a pro-proliferative and invasive tumor cell phenotype." (PMID 30371874, 2019). "This was confirmed in additional tumor-derived cell lines (data not shown) demonstrating that the IGF2BP1-dependent upregulation of SRF expression is highly conserved in cancer cells." (PMID 30371874, 2019).